PARP1 (poly(ADP-ribose) polymerase 1)
Diseases named in the same sentence as PARP1 in open-access papers (continued):
Sharing a sentence is not in itself a finding about the gene and the disease.
multiple sclerosis (14 papers, 2014 to 2025). A progressive autoimmune disorder affecting the central nervous system resulting in demyelination. "In some disease models, such as multiple sclerosis, PARP-1 activity has been proposed to alter leukocyte migration by modifying the expression of adhesion molecules." (PMID 37924373, 2023). "In experimental autoimmune encephalomyelitis (EAE), a murine model of multiple sclerosis, PARP1 deletion increased, while PARP2 deletion reduced EAE-associated neuroinflammation." (PMID 37351597, 2023). "The therapeutic potential of PARP1 inhibition in multiple sclerosis, an inflammatory demyelinating disorder of the central nervous system remains elusive." (PMID 34935305, 2022). "PARP1 and/or its activity are dysregulated in the immune and central nervous system of multiple sclerosis (MS) patients and animal models." (PMID 34935305, 2022). "There are, however, contrasting reports in the literature showing that PARP-1 inhibition by 4-hydroxyquinazoline (4HQ) prevents oligodendrocyte death in diseases such as multiple sclerosis and ischemia." (PMID 35158955, 2022). "PARP-1 activation also leads to the degeneration of OL processes in experimental models of multiple sclerosis." (PMID 29966349, 2018). "Accumulating evidence implicates PARP1 and its enzymatic activity in inflammatory conditions of the central nervous system (CNS) including stroke, multiple sclerosis, and infection." (PMID 25161822, 2014). "Previous reports have shown that inhibition of PARP1 enzymatic activity or deletion of PARP1 is protective in experimental models of multiple sclerosis, ischemia-reperfusion and infection." (PMID 25161822, 2014). "This review highlights the current state and controversies, presents possible interpretations and hypotheses, and points out future research directions in the field of PARP1 regulation of multiple sclerosis pathogenesis." (PMID 34935305, 2022). "In addition, PARP-1 inhibitors demonstrate notable neuroprotective effects in demyelinating disorders, including multiple sclerosis which is considered the archetypical demyelinating disease." (PMID 35158955, 2022). "In the rodent model of multiple sclerosis, experimental allergic encephalomyelitis (EAE), PAR, the marker of PARP-1 activation, accumulates in astrocytes as well as oligodendrocytes, microglia, and neurons, surrounding demyelinated plaques." (PMID 35158955, 2022). "Similarly, overactivation of PARP-1 has been shown in other neurodegenerative diseases, such as HD, ALS and multiple sclerosis." (PMID 35455964, 2022).
rheumatoid arthritis (13 papers, 2006 to 2025). A chronic, systemic autoimmune disorder characterized by inflammation in the synovial membranes and articular surfaces. "In addition to support for this factor coming from the rheumatoid arthritis risk variant CCR6DNP regulating CCR6 via PARP-1, it is interesting to note that a recent age at menopause GWAS linked the loci found in that effort to DNA damage response genes." (PMID 29392078, 2018). "Here we report that the well‐known Au(I) complexes used for decades in the treatment of rheumatoid arthritis are effective PARP‐1 inhibitors." (PMID 41230800, 2025). "We explore in this paper the PARP‐1 inhibition potential of three Au (I) drugs used to treat rheumatoid arthritis—aurothioglucose, sodium aurothiomalate and auranofin." (PMID 41230800, 2025). "In recent years, we have studied the role of PARP-1 in rheumatoid arthritis, as have other researchers, and the results have shown that PARP-1 has an important function in the development of this disease." (PMID 26339143, 2015). "Our results provide evidence of the contribution of PARP-1 to the progression of arthritis and identify this protein as a potential therapeutic target for the treatment of rheumatoid arthritis." (PMID 16356201, 2006). "In animal models, studies aimed at controlling rheumatoid arthritis and cell damage by ischemia/reperfusion through inhibition of PARP-1 activity began as early as in the 1990s, using first (such as nicotinamide) and second generation (PJ34, DPQ) pharmacological inhibitors." (PMID 31877876, 2019). "Interestingly, a recent study also showed that the rheumatoid arthritis GWAS-implicated risk variant, CCR6DNP, regulates CCR6 via PARP-1." (PMID 29392078, 2018). "This review summarizes current knowledge on the effects of PARP-1 in rheumatoid arthritis." (PMID 26339143, 2015). "The role of PARP-1 in auto-reactive immune responses was shown for the first time in experimental models of rheumatoid arthritis (RA), a Th1 cell driven inflammatory autoimmune disease." (PMID 31877876, 2019). "PARP1 (poly(ADP-ribose) polymerase 1 has been extensively investigated for its regulatory role in a variety of inflammatory diseases, including rheumatoid arthritis, systemic lupus erythematosus, inflammatory bowel disease, and acute lung injury." (PMID 40032778, 2025). "Of note, PARP-1 was found to be up-regulated in rheumatoid arthritis (RA)." (PMID 21209926, 2010). "However, despite the well‐established role of PARP‐1 activation in the development of various inflammatory conditions—including pulmonary inflammation and cardiovascular disease—PARP‐1 inhibition by Au(I) compounds has never been considered among their mechanisms of action in rheumatoid arthritis." (PMID 41230800, 2025).
multiple myeloma (12 papers, 2013 to 2025). "A recent GEP study has demonstrated that increased expression of PARP1 is associated with shortened survival in myeloma patients, whereas another GEP study identified the gene as one of 15 which may be used as an expression signature to define high-risk disease." (PMID 24803933, 2014). "Immunohistochemical analysis was carried out in vivo to investigate the effects of the combined PIM‐2 inhibitor SMI‐16a and PARP1 inhibitor ABT888 on multiple myeloma (MM)." (PMID 40557764, 2025). "Meanwhile, inhibition of DTX3L expression has been shown to enhance the sensitivity to chemotherapy and increase the expression of caspase-3 and PARP1 in multiple myeloma cell lines, thus promoting apoptosis." (PMID 34513839, 2021). "In vitro responses in myeloma cell lines and primary patient samples have been studied using the PARP1/2 inhibitor ABT-888." (PMID 29467487, 2018). "To comprehensively elucidate the molecular mechanisms underlying enhanced DNA damage‐induced apoptosis in multiple myeloma (MM) cells through concurrent inhibition of PIM‐2 and PARP1, we performed RNA sequencing on U266 and RPMI‐8226 cell lines following combined treatment with SMI‐16a and ABT888." (PMID 40557764, 2025). "Furthermore, MALAT1 has been shown to modulate the alternative NHEJ (A-NHEJ) pathway by directly interacting with LIG3 and PARP1 in multiple myeloma cells and targeting MALAT1 enhances sensitivity to PARPi or proteasomal inhibitors." (PMID 37812088, 2023). "Moreover, lncRNA MALAT1 was also found to interact with PARP1, influencing the DNA damage and apoptosis in multiple myeloma cells." (PMID 36597139, 2023). "This study investigates how inducing DNA damage in multiple myeloma (MM) cells leads to MICA overexpression, facilitating NKG2D binding on NK cells.We analyzed the relationship between PIM‐2, PARP1, and MM prognosis using public data and clinical samples." (PMID 40557764, 2025). "For example, a recent study revealed that targeting the MALAT1/PARP1 (poly ADP-ribose polymerase 1) / LIG3 (DNA Ligase 3) complex resulted in DNA damage and apoptosis in multiple myeloma." (PMID 36829256, 2023).
retinal degeneration (12 papers, 2010 to 2025). Degeneration of the retina. "The abnormal activation of PARP1 has been clearly confirmed to be a key driver of retinal degeneration." (PMID 41294855, 2025). "Our findings corroborate that PIC-OCT protects photoreceptors by modulating the SIRT1/PARP1 axis in models of retinal degeneration." (PMID 38397799, 2024). "Another study looked at the impact of PARP in retinal degeneration using a Parp1 knockout (Parp1−/−)." (PMID 37601102, 2023). "PARP-1 appears to be responsible for ≈ 90% of cellular PARP activity and a previous study from our group found PARP-1 knockout retina to be resistant against cGMP-induced retinal degeneration." (PMID 37189329, 2023). "In other sensory systems, such as the retina, PARP1 gene knock-out increases resistance to retinal degeneration, and PARP inhibitors, including the anti-cancer drug olaparib, improve retinal viability." (PMID 31551715, 2019). "Parp1 gene deletion completely rescued the MMS-induced retinal degeneration in male mice and in female Parp1−/− mice as well." (PMID 28978150, 2017). "Collectively, we report that AIF-independent PARP-1-dependent necrosis constitutes a major mechanism of RPE cell death leading to retinal degeneration in dry AMD." (PMID 28055012, 2017). "Even though female mice are partially protected against alkylation-induced retinal degeneration compared to male mice, Parp1 gene deletion completely rescued both males and females against alkylation-induced retinal and cerebellar degeneration." (PMID 28978150, 2017). "Recent studies have shown that several caspase-independent inducers of cell death such as apoptosis-inducing factor (AIF), calpains, and poly(ADP-ribose) polymerases 1 (PARP-1) are activated during retinal degeneration." (PMID 21670490, 2011). "PARP1 KO prevented photoreceptor cell death in vitro, a result that highlights the importance of PARP1 as a novel therapeutic target in retinal degeneration both for pharmacological and genetic treatment approaches." (PMID 21124852, 2010). "While wt photoreceptors were highly susceptible to a stress paradigm mimicking the rd1 type of inherited retinal degeneration, PARP1 KO photoreceptors were resistant to such stress." (PMID 21124852, 2010). "In the rd1 mouse model, retinal degeneration starts at around P11 and consequently we chose this time-point for a comparative analysis of different cell death markers in wt, rd1, and PARP1 KO retina." (PMID 21124852, 2010). "In addition, cell death significantly decreased in PARP1 knockout mouse retina explants treated with a selective PDE6 (photoreceptor phosphodiesterase) inhibitor to induce retinal degeneration." (PMID 38397799, 2024). "The observed resistance to PDE6 induced retinal degeneration in Parp1−/− mutants suggests that PARP1 may be involved in photoreceptor degeneration via PARP-mediated cell death or a closely related mechanism." (PMID 37601102, 2023). "The retina of the Parp1−/− mouse line was found to be morphologically similar to wildtype; however, there was a significant resistance to retinal degeneration when induced by blocking phosphodiesterase 6 (PDE6), an essential component of the phototransduction pathway." (PMID 37601102, 2023). "Moreover, we also validated the in vivo role of PARP-1 in retinal degeneration using Si-injected mice and rabbits." (PMID 28055012, 2017). "Collectively, our data show that PARP-1 mediates retinal degeneration in a dry AMD mouse model." (PMID 28055012, 2017). "While, the retina of PARP1 KO animals appeared essentially normal in terms of morphology and function, photoreceptor cell death was greatly decreased under a specific stress paradigm that mimics inherited retinal degeneration." (PMID 21124852, 2010). "Parp1 gene deletion in AagTg mice (Parp1−/−/AagTg) completely rescued the MMS-induced retinal degeneration, regardless of gender." (PMID 28978150, 2017).
serous ovarian cancer (12 papers, 2013 to 2023). "DNA from BRCA-mutated serous ovarian cancer samples and adjacent normal ovarian tissues were analyzed by bisulfite sequence using primers focusing on the CpG island in the promoter region of PARP1." (PMID 23442605, 2013). "Furthermore, a study published by Barnett JC revealed that high expression of PARP1 in serous ovarian cancers is associated with worse OS." (PMID 35875162, 2022). "Seventy-two patients with high-grade serous ovarian cancer were included in the retrospective analysis of our study to determine the relationship between PARP1, PD-L1, and CD8." (PMID 34620163, 2021). "We observed that PARP1 is overexpressed in high-grade serous ovarian carcinoma when compared to fallopian tubes and PARP1 inhibition greatly reduced the proliferation of cancer cells." (PMID 29684820, 2018). "Western blot analysis of proteins extracted from high-grade serous ovarian cancer (HGSOC) and fallopian tubes (FT) showed that PARP1 levels were much higher in HGSOC tissues than in FT." (PMID 29684820, 2018). "Differently than what we observed, that study indicated a negative correlation between the PARP1/ARTD1-dependent ADPR levels and the clinical outcome of high grade serous ovarian cancer patients." (PMID 33742140, 2021).
cholangiocarcinoma (11 papers, 2017 to 2025). A carcinoma that arises from the intrahepatic biliary tree (intrahepatic cholangiocarcinoma) or from the junction, or adjacent to the junction, of the right and left hepatic ducts (hilar cholangiocarcinoma). "In a search of the GEPIA database (Accessed May 2, 2020), mRNA expressions of FAM83H/ZNF16 was significantly associated with PARP1 mRNA expression in cholangiocarcinoma (FAM83H versus PARP1; Pearson correlation, R = 0.45, p = 0.005, ZNF16 versus PARP1; Pearson correlation, R = 0.34, p = 0.045)." (PMID 32460791, 2020). "This study shows that USP1 stabilizes PARP1 via K197 deubiquitination, fueling cholangiocarcinoma growth and metastasis." (PMID 41301681, 2025). "The expression of cleaved Caspase-3 and cleaved PARP1 significantly increased after silibinin treatment, which means that silibinin induced cholangiocarcinoma cell death by activating apoptosis pathways." (PMID 35401195, 2022). "When the IC50 concentration of HCQ was used for cholangiocarcinoma administration, we confirmed that the number of apoptotic cells and the expression of apoptosis-related proteins (cleaved caspase 3 and cleaved PARP1) increased significantly, accompanied by G1 phase arrest." (PMID 34568426, 2021). "Under hypoxic conditions, SKA3 recruits PARP1 to bind with HIF-1α, thereby enhancing USP7-mediated deubiquitination of HIF-1α, promoting the proliferation and fatty acid synthesis of cholangiocarcinoma cells." (PMID 39944823, 2025). "Studying the effects of PARP1 inhibition in the other BAP1-mutant malignancies, such as renal cell carcinoma and cholangiocarcinoma, would be especially important, since cancers also have little beneficial therapy once initial resection has failed." (PMID 28756516, 2017). "The protein expression levels of USP1 and PARP1, as well as the acetylation status of USP1-K130, could serve as potential prognostic biomarkers to guide precision stratification therapy in cholangiocarcinoma." (PMID 41301681, 2025). "Although previous studies have reported that SKA3 interacted with PARP1/HIF-1α to promote cholangiocarcinoma proliferation, our findings did not reveal a direct interaction between SKA3 and HIF-1α in LUAD." (PMID 41298345, 2025). "Moreover, USP1 is upregulated in cholangiocarcinoma (CCA) and its positive regulation of PARP1 leads to increased proliferation, invasion, and metastasis in CCA models." (PMID 37821462, 2023).
Cognitive impairment (11 papers, 2016 to 2025). Abnormal cognition is characterized by deficits in thinking, reasoning, or remembering. "We found that PARP-1 KO mice display emotional and cognitive deficits associated with schizophrenia-like behaviors." (PMID 31819047, 2019). "The loss of nucleolar PARP-1 may explain the finding that rDNA genes are hypermethylated in mild cognitive impairment (MCI) and AD." (PMID 31827497, 2019). "This loss of nucleolar PARP-1 from hippocampal pyramidal neurons may lead to deficits in synaptic plasticity and, thus, to cognitive impairment." (PMID 27034851, 2016). "This dysregulation has been associated with cognitive impairments observed both in this study and in previous TBI models, where PARP1 inactivation alleviated such deficits." (PMID 40963678, 2025). "PARP1 depletion protects the brain against Aβ-evoked microglia activation, hippocampal synaptic integrity alteration, and cognitive impairment using hAPPJ20 mice crossed with PARP1−/− mice." (PMID 35806303, 2022). "Administration of Gra-b inhibitor annulled the upregulation of Gra-b, cleaved Caspase-3, and cleaved PARP1 levels, thus ameliorating neuronal apoptosis as well as behavioral and cognitive impairment." (PMID 31920929, 2019). "We proposed that the displacement of PARP-1 from the nucleolus results in downregulation of new rRNA expression and ribosome biogenesis, leading to cognitive impairment." (PMID 31827497, 2019). "To further investigate the relationship between nucleolar PARP-1 and memory impairment, we examined PARP-1 expression in the hippocampi of individuals with mild cognitive impairment (MCI) compared to control and AD cases." (PMID 31827497, 2019). "Here, we compared the expression of BER components APE1, OGG1, PARP1 and Polβ in blood and postmortem brain tissue from patients with AD, mild cognitive impairment (MCI) and healthy controls (HC)." (PMID 27234294, 2016). "To investigate whether nucleolar PARP-1 could function as an early marker of cognitive impairment, we examined PARP-1 levels in the hippocampi of individuals with MCI compared to Control and AD cases." (PMID 31827497, 2019). "Reduced nucleolar diameter found in PARP-1 positive nucleoli, but not all (H&E stained) nucleoli, supports the hypothesis that PARP-1 could be a marker of early cognitive impairment." (PMID 31827497, 2019). "Interestingly, PARP-1 knockout mice exhibited schizophrenia-like symptoms such as anxiety, depression, social interaction deficits, cognitive impairments, and prepulse inhibition deficits." (PMID 31819047, 2019). "The data presented here is consistent with our hypothesis and provides evidence that decreased nucleolar PARP-1 is an early marker of cognitive impairment." (PMID 31827497, 2019). "Interestingly, such a decrease in PARP1 staining was revealed in neurons of individuals with mild cognitive impairment (MCI), suggesting that decreased nucleolar PARP1 could act as an early biomarker of cognitive impairment." (PMID 32640701, 2020).
pulmonary hypertension (11 papers, 2017 to 2024). Increased pressure within the pulmonary circulation due to lung or heart disorder. "It has also been shown that the activation of Poly ADP-ribose polymerase-1 (PARP1) due to inflammation results in pulmonary hypertension associated with decrease in miR-204 levels." (PMID 32660602, 2020). "Taken together, these data implicate the PARP1/PKM2 axis as a critical driver of maladaptive RV remodeling and a new promising target to directly sustain RV function in patients with pulmonary arterial hypertension." (PMID 35540097, 2022). "The overexpression of Poly (ADP)-ribose-1 (PARP-1), a component/marker of the DNA repair/damage, designates pulmonary artery smooth muscle cells (PAH-PASMCs) in pulmonary hypertension." (PMID 35684428, 2022). "The authors show that increased poly(adenosine diphosphate–ribose) polymerase 1 (PARP1) and pyruvate kinase muscle isozyme 2 (PKM2) expression is a common feature of a decompensated right ventricle in patients with pulmonary arterial hypertension and animal models." (PMID 35540097, 2022). "Furthermore, based on previous data showing that miR-223 regulates PARP-1 expression in a model of pulmonary hypertension, they proposed that a negative feedback loop exists between PARP proteins and miR-223 in lung adenocarcinoma." (PMID 39125761, 2024). "Olaparib is already available for the treatment of cancer and is also being investigated as a potential therapy for pulmonary arterial hypertension (Clinical Trial No.: NCT03782818), although these applications focus on DNA damage and repair features of PARP1/ARTD1 inhibition." (PMID 37513811, 2023).